TNF (tumor necrosis factor)
Diseases named in the same sentence as TNF in open-access papers (continued):
Sharing a sentence is not in itself a finding about the gene and the disease.
peripheral neuropathy (continued). "First, a single injection of D-mannose creates transient but complete reversal of allodynia in an animal model of peripheral neuropathy mediated by TNF-α, IL-1β and NO actions." (PMID 24884664, 2014). "In painful peripheral neuropathies significantly higher blood levels of IL-2 mRNA and TNF-α mRNA were measured compared to healthy subjects." (PMID 23383716, 2013). "In our study we have examined the possible role of TNFα in modulation of synaptic transmission at superficial DH neurons in a model of peripheral neuropathy." (PMID 22189061, 2011). "In the present experiments the effect of TNFα incubation on modulation of primary afferent synaptic activity was investigated in a model of peripheral neuropathy." (PMID 22189061, 2011). "We have herein provided evidence that redox-active Mn porphyrin, BMX-001 (MnTnBuOE-2-PyP5+), bears therapeutic potential for reducing chemotherapy-induced peripheral neuropathy at clinically relevant dosing via microglia/TNF-α signaling involved in suppression of neuroinflammation." (PMID 40900760, 2025). "Peripheral neuropathy of the sciatic nerve increased TNF‐α, IL‐1β, IBA‐1, and CD11b." (PMID 37786517, 2023). "Diagnosis of peripheral neuropathy in the course of anti-TNF-alpha treatment." (PMID 35054511, 2022). "Additionally, it has been reported that ST shows neuroprotective properties via reducing inflammatory mediators such as caspase-3, IL-1β, and tumor necrosis factor α (TNFα) in the dorsal ganglion of animals with vincristine-induced peripheral neuropathy." (PMID 35075426, 2022). "sEPSC frequency is indicative of spontaneous synaptic vesicle transmission and of synaptic status in pain conditions including spinal nerve ligation, painful diabetic neuropathy, central and peripheral inflammatory pain from TNF-α, and chemotherapy-induced peripheral neuropathy." (PMID 34867259, 2021). "Paclitaxel increases IL-6, TNF-α, and CCL2 production in dorsal root ganglia neurons, and IL-6 neutralizing antibody pretreatment prevents peripheral neuropathy development, suggesting the role of increased inflammation in peripheral neuropathy development." (PMID 40759570, 2025). "Tumor necrosis factor-alpha (TNF-α) is a well-known inflammatory cytokine and potential mediator for the development of peripheral neuropathy." (PMID 35596774, 2022). "Taken together, it is worth noting that TNF-α and IL-6 in plasma and phospho-NF-κB and phospho-STAT3 in spinal cord and sciatic nerves are putative biomarkers of docetaxel-induced peripheral neuropathy (DIPN) in mouse models." (PMID 34422067, 2021). "Several studies demonstrated increased TNFα levels in DRG and spinal cord in different models of peripheral neuropathy." (PMID 22189061, 2011). "PRP or PRP gel has not been shown to suppress neuronal expression of TNF-α and IL-6 in peripheral neuropathy animal models." (PMID 40951078, 2025). "Finally, serum TNF levels are higher in T2DM patients with peripheral neuropathy as compared to T2DM patients without peripheral neuropathy, providing further support for an inflammatory component in development of peripheral neuropathy in T2DM." (PMID 32604774, 2020). "Despite these reports of favorable effects with the use of anti-TNF-α drugs on peripheral nerve disorders, some researchers suspect that such drugs may have negative side effects for patients with peripheral neuropathies." (PMID 23469058, 2013). "Sequestration of TNFα via either an anti-TNF antibody or the soluble form of the TNF receptor is capable of modulating TNFα activity; moreover, this therapeutic strategy has demonstrated some promise in pre-clinical models of lumbar radiculopathy and peripheral neuropathy." (PMID 21871102, 2011).
liver (53 papers, 2006 to 2026). "The TNF-TNFR axis probably contributes to the development of chronic inflammation-associated colon carcinogenesis process." (PMID 28408791, 2017). "Furthermore, CSE regulation of TNF-α-controlled intracellular signaling pathways could provide new therapeutic targets in diseases of the colon associated with impaired epithelial wound healing." (PMID 39334726, 2024). "Elevated levels of inflammatory factors, such as tumor necrosis factor-α (TNF-α), interleukin-1 (IL-1), and IL-6, have the potential to initiate colon carcinogenesis." (PMID 37835359, 2023). "Novel data have identified TNF-α, IL-17A and IL-6 as crucial link between enhanced activity of immune system and colon carcinogenesis." (PMID 28881574, 2017). "Furthermore, an analysis of the effects of PCE on IL-6, IL-1β, and TNF-α expression in colonic epithelial cells of the rat colon carcinogenesis model showed an increase in IL-6, IL-1β, and TNF-α mRNA levels in the DMH + DSS group." (PMID 36900505, 2023). "Moreover, L. rhamnosus treatment can reduce the expression of β-catenin and the inflammatory proteins NFκB-p65, COX-2 and TNF-α in dimethyl hydrazine (DMH)-induced colon carcinogenesis." (PMID 35215376, 2022). "Additionally, the essential involvement of a transcription factor, NF-κB, in this colon carcinogenesis model prompted us to investigate the intracolonic expression of TNF-α as it is a potent activator of NF-κB." (PMID 33776762, 2021). "An explanation of this result could be that elevated TNF-α in process of colon carcinogenesis due to many other inducers of TNF-α synthesis, evoke activation of different transcription factors which mask the individual effect of –308G/A polymorphism in TNF-α." (PMID 26019577, 2014). "The ethanol extract can improve the levels of serum TNF-α and IL-2 in mice, boost SOD activity, and decrease MDA content; thus, it can against the growth of digestive tumor cells with an inhibition activity of 68.84%." (PMID 39275063, 2024). "We further found NOTCH3 levels in gastrointestinal tumor to correlate with markers of Dendritic cell(HLA-DPB1, HLA-DRA, HLA-DPA1, BDCA-4), Tfh(T-bet, STAT4, STAT1, TNF-α), Treg cells (FOXP3, CCR8, STAT5B, TGFβ) and T cell exhaustion (PD-1, CTLA4, LAG3, TIM-3)." (PMID 38906903, 2024). "Berberine can reduce the expression of pro-inflammatory cytokines IL-1, IL-6 and TNF- mRNA and CD68(markers of macrophages) in MICE with DSS-colonitis." (PMID 33019433, 2020). "This agrees with previous studies which have shown IL-1 and TNFα stimulate mucin secretion via IL-1R1 on the basolateral surface of cultured HT29-C1.6E cells and via NF-KappaB pathway in HM3 colon cancer cells." (PMID 30755679, 2019). "The inflammation-related cytokines, interleukin (IL)-6, IL-12, tumor necrosis factor (TNF)-α and interferon (IFN)-γ, were used to analyze these preventative effects on azoxymethane (AOM)- and dextran sulfate sodium (DSS)-induced colon carcinogenesis in mice." (PMID 24396476, 2014). "It is widely reported that cytokines (IL1β, TNF-α), matrix metalloproteinase (MMP-7, MMP-9) are involved in chronic inflammation, which creates a microenvironment favoring colon carcinogenesis." (PMID 23754197, 2013). "The agent was found to decrease the production of Tumor Necrosis Factor alpha (TNFα) and Interleukin-1β (IL-1β) in peritoneal macrophages as well as the TNFα and the VEGF secretion by gastrointestinal neoplasms." (PMID 16796759, 2006).
intestinal disease (48 papers, 2011 to 2025). "It is well reported that proinflammatory cytokines such as TNF-α disrupts the intestinal epithelial barrier functions both in vitro and in vivo, causing intestinal disorders." (PMID 35130890, 2022). "TNF-α is a prominent pro-inflammatory cytokine associated with inflammatory state and intestinal diseases." (PMID 32150574, 2020). "Proinflammatory cytokines such as IL-6, IL-8, and TNF-α are associated with the severity of inflammation and intestinal disease, which can directly affect intestinal epithelial cells." (PMID 33163144, 2020). "Most neurological complications occur with active intestinal disease, and there is a significant risk posed by more recent biologic therapies including monoclonal antibodies that target tumor necrosis factor, TNF." (PMID 30937208, 2019). "It normally causes mucosal inflammation, intestinal ulcers, and histological damage and triggers colonic expression of the proinflammatory cytokines TNF-α, IL-1β, and IL-6 in 14 days after the TNBS administration." (PMID 25729217, 2015). "Intestinal ulcers associated with CD are primarily located at the mesenteric margin, and increased TNF-α production by fat cells in mesenteric fat may contribute to transmural inflammation." (PMID 37296832, 2023). "Together, these results indicate that intestinal disease-associated Tc17 cells represent a distinct population of inflammatory CD8+ T cells prone to co-produce TNF that can be further functionally subdivided into three subpopulations based on IFN-γ, IL-22 and XCL-1 production." (PMID 35760777, 2022). "During piglet production, weanling stress may induce intestinal disorders with increased pro-inflammatory cytokine secretion such as IL-1β, IL-6, and TNF-α, which cause growth retardation." (PMID 35814707, 2022). "Moreover, weaning is associated with upregulation of IL-1, Il-6, and TNF-α in the intestine, and this early inflammatory response may contribute to both anatomical and functional intestinal disorders in piglets." (PMID 25101851, 2014). "These intestinal disorders are promoted by the release of pro-inflammatory cytokines (TNF-α, IL-1β, and IFN- γ) that inhibit the mRNA expression of TJ proteins." (PMID 38019021, 2024). "Intestinal ulcers were almost healed after inducing therapy with steroids and maintenance treatment of anti-TNFα therapy." (PMID 35754805, 2022). "Bacterial diarrhea is an intestinal disease mediated by the overproduction of proinflammatory cytokines, including IL-1β, TNF-α, etc.." (PMID 35696408, 2022). "Pro-inflammatory cytokines, such as IL-1β, IL-6, and TNF-α, serve to stimulate inflammatory responses and promote the occurrence of intestinal diseases." (PMID 36359981, 2022). "In fact, anti-TNF-α agents, such as infliximab, are highly effective in the treatment of moderate to severe intestinal disease." (PMID 34452089, 2021). "TNF-α was used to stimulate pro-inflammatory cytokine secretion in IEC-6 cells to imitate its elevation in some intestinal diseases." (PMID 33593395, 2021). "TNF-α and IL-6 in the serum are related to intestinal disease, and all are upregulated in IBD patients." (PMID 32714090, 2020). "Together with the failure of a ligand-incompetent hLRH-1 mutant to protect against TNFα-damage, these findings provide compelling evidence that hLRH-1 mediates epithelial homeostasis and is an attractive target for intestinal disease." (PMID 30305617, 2018). "Oral administration of the prominent gut microbe Faecalibacterium prausnitzii has recently been discovered to show anti-inflammatory properties by increasing the production of IL-10 (a cytokine) and tumor necrosis factor (TNF) in the colon to improve intestinal disease." (PMID 36983881, 2023).
intestinal disease (continued). "Actually, aberrant innate and adaptive inflammatory responses are common consequences in intestinal diseases, mostly represented by the activation of NF-κB and up-regulated levels of pro-inflammatory cytokines, including tumor necrosis factor α (TNF-α), interferon γ (IFN-γ), and interleukins." (PMID 37298531, 2023). "Increased TNF-α due to intestinal disease stimulates the secretion of IFN-γ in IBD patients." (PMID 32714090, 2020). "Finally, all the T cells at mucosal level were able to produce large amount of TNF-α, suggesting that its production is a peculiar property of intestinal T cells of patients with early active intestinal disease." (PMID 27930541, 2016). "Finally, all the T cells at mucosal level were able to produce large amount of TNF-α, suggesting that its production is a property of intestinal T cells of patients with early active intestinal disease." (PMID 27930541, 2016). "Tumor necrosis factor-alpha (TNF-α), a pro-inflammatory cytokine, is locally and systemically high in patients with intestinal diseases and is known to increase inflammatory responses and TJ permeability." (PMID 35741912, 2022). "As an indicator of more intensive intestinal disease activity, patients with cutaneous manifestations of IBD needed more frequently therapy with antibiotics, steroids, immunomodulators and anti-TNF." (PMID 30682031, 2019). "TNF-α production by human macrophages was discovered in the colonic tissue in patients with CD and UC, and there is linear correlation between serum levels of TNF-α with clinical and laboratory indices of intestinal disease activity." (PMID 36384756, 2022). "In summary, we characterized LPS, TNF-α, and IL-17 levels using histopathological and morphological observations of H&E sections, ELISA, and LPS levels to preliminarily investigate the alleviating effects of GOS on the intestinal barrier of mice with an intestinal disorder." (PMID 38005333, 2023). "However, CGRP, whose role in intestinal diseases has not been fully elucidated, may inhibit the expression of TNF-α and IL-1β and take part in mechanisms connected with the development of diarrhoea." (PMID 30154361, 2018).
inflammatory myopathies (41 papers, 2010 to 2026). "Clinicians should remain vigilant when using TNF inhibitors in patients predisposed to inflammatory myopathies." (PMID 40861474, 2025). "Elevated circulating TNFα in obese individuals can especially lead to muscle loss and inflammatory myopathies by regulating the activation and secretion of other inflammatory cytokines." (PMID 32316567, 2020). "Second, clinicians should be aware of the ever-increasing armamentarium of therapies (such as TNF inhibitors) in chronic inflammatory disease states (such as RA or inflammatory myopathies), and that these together may pose a cumulative risk for malignancy." (PMID 28210638, 2017). "In the present study, the protective effect of DPHC on TNF-α -induced inflammatory myopathy was investigated in an in vivo zebrafish model." (PMID 41149579, 2025). "A range of inflammatory cytokines are found upregulated in sIBM compared to healthy muscle or other inflammatory myopathies, including interferon γ (IFNγ), tumor necrosis factor α (TNFα), interleukin (IL)-7, and IL-32." (PMID 37731843, 2023). "Global deletion of 11β-HSD1 has previously been shown to exacerbate myopathy in the inflammatory model of TNF-tg mice but protect against myopathy in the glucocorticoid excess model of WT mice receiving oral corticosterone." (PMID 34360594, 2021). "To corroborate these results, we analyzed several inflammatory cytokines like IL-8, TNF-α, IL-1β and IL-17A in the plasma of these inflammatory myopathy patients following IVIG therapy." (PMID 31974400, 2020). "In this study, therefore, we analyzed the protective activity of DPHC against TNF-α-induced inflammatory myopathy through p65 NF-κB and MAPKs pathways in C2C12 cells." (PMID 33114618, 2020). "As the results, DPHC down-regulated the protein expression levels of MuRF-1 and MAFbx/Atrogin-1, which are the key protein of muscle atrophy through NF-κB and MAPKs signaling pathways in TNF-α-stimulated inflammatory myopathy C2C12 cells." (PMID 33114618, 2020). "It was expected that DPHC is therefore a promising candidate for the development of safe pharmacological agent that have potent inhibitory effects against inflammatory myopathy by TNF-α instead of synthetic drugs." (PMID 33114618, 2020). "TNFα was significantly inversely correlated with decreased myogenic miRNA expression in the inflammatory myopathy subtypes." (PMID 29321815, 2018). "The major role of TNF-alpha in inflammatory and non-inflammatory myopathies is on the whole suggested to be related to regeneration of the muscle fibers." (PMID 29183282, 2017). "A similar pattern of dysregulation of miR-1, 133a, 133b and 206 has been reported in inflammatory myopathies and in a cell culture system in which TNF-α reduced expression of these myomiRs." (PMID 27907012, 2016). "Considering the rarity of the linkage between RA and inflammatory myopathies (DM/PM), most of the cases analyzed in the present study might not represent a sporadic association because of the history of introduction of an anti-TNF-α agent and the improvement after withdrawal of the drug." (PMID 24600322, 2014). "A screening for detecting potentially valuable inhibitors of NF-κB, in order to block TNFα activity and identify non toxic optimal therapies for the inflammatory myopathies, has been repoted in a murine cell line." (PMID 24204948, 2013). "Expression of TNF-alpha in macrophages has previously been noted in other situations, including inflammatory myopathies." (PMID 22505941, 2012). "Idiopathic inflammatory myopathies stem from imbalances in cytokine signaling and T-cell dysregulation, creating a proinflammatory environment which fuels the disease process, including IFNs, TNF-alpha, janus kinases, IL-6, etc." (PMID 40297385, 2025). "In addition, IO can potentially inhibit tumor necrosis factor (TNF)-α in muscle-degradation-induced inflammatory myopathy." (PMID 35621931, 2022).